LACTB (lactamase beta)
Diseases named in the same sentence as LACTB in open-access papers (continued):
Sharing a sentence is not in itself a finding about the gene and the disease.
glioma (7 papers, 2018 to 2025). A benign or malignant brain and spinal cord tumor that arises from glial cells (astrocytes, oligodendrocytes, ependymal cells). "Emerging evidence indicates that LACTB expression progressively declines with advancing glioma grade." (PMID 39941048, 2025). "In contrast, the overexpression of LACTB was shown to suppress tumor cell proliferation, invasion, and angiogenesis, suggesting its potential role as a therapeutic target in glioma treatment." (PMID 39941048, 2025). "Similar results were obtained for gliomas where the degree of LACTB downregulation correlated with an unfavourable overall clinical outcome, and in glioma cell lines LACTB overexpression resulted in an inhibition of cell proliferation." (PMID 35626737, 2022). "LACTB expression is decreased in glioma;Low LACTB expression is correlated with a poor prognosis of glioma patients;Overexpressing LACTB suppresses the proliferation, invasion, and angiogenesis of glioma cells." (PMID 36078157, 2022). "Notably, the expression of LACTB is significantly reduced in glioblastoma, the most aggressive and lethal form of glioma, when compared to normal neural tissues." (PMID 39941048, 2025). "In gliomas, a downregulation of LACTB leads to an increase in cancer cell proliferation and angiogenesis, corresponding to a poor prognosis in patients, while its overexpression does the opposite by inhibiting PCNA, MMP2, MMP9, and VEGF, which are key regulators in glioma cell proliferation." (PMID 34361072, 2021). "Recent studies suggested that downregulated LACTB promoted cell proliferation in BRCA and glioma." (PMID 29790671, 2018). "In addition, the overexpression of LACTB can inhibit the expression of PCNA, MMP2, MMP9 and VEGF, which are believed to play an important role in the proliferation, invasion and angiogenesis of glioma cells." (PMID 33507917, 2021).
liver cancer (7 papers, 2018 to 2025). An epithelial or non-epithelial malignant neoplasm that arises from the liver. "In this study, we tested the expression levels of LACTB in liver cancer and investigated its biological functions and underlying mechanisms." (PMID 39047638, 2024). "Similarly, LACTB overexpression was associated with increased sensitivity to docetaxel in lung cancer cells and enhanced the antitumor efficacy of lenvatinib in liver cancer samples." (PMID 39941048, 2025). "Notably, one study proposed that LACTB is downregulated in liver cancer, which is associated with a poor prognosis; however, the mechanism by which LACTB acts has not been elucidated." (PMID 39047638, 2024). "Here, we found that serine beta-lactamase-like protein (LACTB) inhibits liver cancer progression by regulating ferroptosis." (PMID 39047638, 2024). "The Clinical Proteomic Tumour Analysis Consortium (CPTAC) database also shows a decrease in LACTB protein expression in liver cancer." (PMID 39047638, 2024). "Overall, these data suggested that LACTB retarded liver cancer cell growth both in vitro and in vivo." (PMID 39047638, 2024). "Taken together, these data suggested that HSPA8 was responsible for the regulatory effects of LACTB on ferroptosis in liver cancer cells." (PMID 39047638, 2024). "LACTB is downregulated in liver cancer, and the ectopic expression of LACTB markedly inhibits cell viability, colony formation, and tumour growth." (PMID 39047638, 2024). "Collectively, these results indicate that LACTB is a potential driver of ferroptosis in liver cancer." (PMID 39047638, 2024). "Taken together, our study reveals a novel action of LACTB and provides potential therapeutic strategies for enhancing the efficacy of lenvatinib in liver cancer." (PMID 39047638, 2024). "We first tested LACTB expression in ten pairs of freshly frozen tissues and found that LACTB protein was significantly downregulated in liver cancer tissues compared to that in the adjacent normal tissues." (PMID 39047638, 2024). "Recent studies demonstrate LACTB inhibits liver cancer progression by regulating ferroptosis." (PMID 40920657, 2025). "Notably, SCOT mediates Ksucc on mitochondrial protein LACTB, leading to enhanced mitochondrial membrane potential and respiration in liver cancer cells." (PMID 39554048, 2025). "Several studies have shown that HSPA8 inhibits ferroptosis by promoting SLC7A11/GSH/GPX4 signalling and inhibiting NCOA4-mediated ferritinophagy, We verified the effects of HSPA8 in liver cancer and found that LACTB promotes ferroptosis by regulating HSPA8-mediated ferroptosis-related signalling." (PMID 39047638, 2024). "Taken together, our findings provide robust evidence that LACTB is an intrinsic inducer of ferroptosis, and that restoration of LACTB may be a potentially effective therapeutic approach against liver cancer." (PMID 39047638, 2024).
liver cancer (continued). "Furthermore, paraffin-embedded tissues were collected for IHC staining, and the results showed that LACTB was expressed at low levels in liver cancer cases." (PMID 39047638, 2024). "Therefore, we inferred that LACTB represses liver cancer via ferroptosis." (PMID 39047638, 2024). "Hence, we assumed that LACTB expression was the same in liver cancer." (PMID 39047638, 2024). "Overexpression of HSPA8 notably abolishes the antitumour effect of LACTB, suggesting that HSPA8 is an oncogene in liver cancer." (PMID 39047638, 2024). "A low expression of LACTB protein was observed in BRCA tissues compared with matched adjacent non‐tumor tissues by Pan‐cancer TMA analysis, as well as in liver cancer." (PMID 29790671, 2018). "A low expression of LACTB protein was observed in BRCA and liver cancer, indicating a tumor‐specific expression pattern of LACTB." (PMID 29790671, 2018). "Notably, a recent study showed that extensive succinylation of LACTB K284, induced by OXCT1, inhibits LACTB activity and promotes cancer progression, implying a strong link between LACTB and liver cancer." (PMID 39047638, 2024).
nasopharyngeal carcinoma (6 papers, 2022 to 2025). A carcinoma arising from the nasopharyngeal epithelium. "Elevated LACTB expression in S18 cells has been associated with enhanced nasopharyngeal carcinoma progression." (PMID 39941048, 2025). "Notably, high LACTB levels are frequently associated with distant metastasis and treatment failure, emphasizing its potential role in the progression of nasopharyngeal carcinoma." (PMID 39941048, 2025). "However, in certain cancers, such as nasopharyngeal carcinoma and pancreatic adenocarcinoma, LACTB expression is abnormally elevated and strongly associated with poor patient survival rates." (PMID 39941048, 2025). "Research on nasopharyngeal carcinoma has revealed that LACTB expression is significantly elevated in cancer tissues compared to adjacent normal tissues." (PMID 39941048, 2025). "Elevated LACTB expression correlates with the aggressive behavior of nasopharyngeal carcinoma and reduces overall survival in patients." (PMID 39941048, 2025). "In this context, silencing LACTB can inhibit the metastasis of nasopharyngeal carcinoma by inhibiting ERBB3/EGFR signal transduction and increasing the stability of histone H3." (PMID 38149985, 2023). "In nasopharyngeal carcinoma and pancreatic cancer, high LACTB expression has been reported to promote malignant behavior of cancer cells and serve as an unfavorable prognostic indicator." (PMID 38149985, 2023). "In nasopharyngeal carcinoma cells, LACTB expression is distinctly regulated by DNA methylation." (PMID 39941048, 2025). "Accordingly, upregulation of LACTB expression promotes the migratory and invasive potential of gastric cancer cells, while downregulation of LACTB expression impedes these abilities, consistent with previous investigations on LACTB in nasopharyngeal carcinoma." (PMID 38149985, 2023). "However, recent research has revealed that LACTB expression levels are upregulated in nasopharyngeal carcinoma and pancreatic cancer, and it can potentially enhance the invasive, migratory, and proliferative abilities of cancer cells." (PMID 38149985, 2023). "However, there are certain tumors where LACTB is expressed at a high level, such as in nasopharyngeal carcinoma." (PMID 38149985, 2023). "In the low-metastatic parental nasopharyngeal carcinoma cell line CNE-2, the DNA in the 5′ promoter region of LACTB is highly methylated, leading to suppressed mRNA transcription of LACTB." (PMID 39941048, 2025). "However, in nasopharyngeal carcinoma (NPC) and pancreatic adenocarcinoma (PAAD), LACTB is highly expressed and correlated with poor patient survival." (PMID 36078157, 2022).
colon cancer (4 papers, 2022 to 2025). "Parallelly, in colon cancer, miRNA-1276 promotes cell proliferation by inhibiting LACTB." (PMID 36078157, 2022). "LACTB is inhibited miR-1276 inhibits in colon cancer cells, which inhibits autophagy." (PMID 36078157, 2022). "LACTB mRNA expression is lower in colon cancer than in normal tissue;Overexpressing miR-1276 in colon cancer cells increases proliferation, migration, invasiveness, and epithelial-to-mesenchymal transition and decreases apoptosis, while supplementing LACTB suppresses these effects of miR-1276." (PMID 36078157, 2022).
gastric cancer (4 papers, 2022 to 2025). A primary or metastatic malignant neoplasm involving the stomach. "Additionally, the expression level of LACTB transcript variant 1 can significantly affect the migratory and invasive potential of gastric cancer cells." (PMID 38149985, 2023). "Establishing a reference range for transcript variant 1 expression levels in healthy individuals may facilitate the detection of LACTB transcript variant 1 expression in peripheral blood of gastric cancer patients, potentially aiding in disease diagnosis." (PMID 38149985, 2023). "Furthermore, our study sought to explore the mechanism underlying LACTB-mediated autophagy involved in the EMT of gastric cancer cells." (PMID 38149985, 2023). "This analysis indicated that LACTB transcript 1 may possess diagnostic value for gastric cancer." (PMID 38149985, 2023). "In gastric cancer, LACTB suppresses autophagy, thereby modulating immune resistance and cancer stemness, emphasizing its significance in precision oncology." (PMID 39941048, 2025). "According to relevant studies, transcriptional analysis of LACTB in gastric cancer tissues and peripheral blood from gastric cancer patients revealed that LACTB transcript 1 is significantly upregulated compared to healthy individuals." (PMID 39941048, 2025). "We collected venous peripheral blood from 93 gastric cancer patients and 82 healthy controls to extract RNA and quantify the expression levels of different transcripts of LACTB." (PMID 38149985, 2023). "Functional modules of LinkedOmics were utilized to analyze the co-expressed genes of LACTB in gastric cancer, and the results are visualized in a volcano plot." (PMID 38149985, 2023). "In the peripheral venous blood of gastric cancer patients, the expression level of LACTB transcript 1 was significantly higher than that in the healthy controls (P<0.05)." (PMID 38149985, 2023). "Collectively, these findings provide compelling evidence that LACTB can modulate the autophagy of gastric cancer cells by regulating the autophagy signaling pathway." (PMID 38149985, 2023). "An examination of the data unveiled a notably elevated expression level of LACTB mRNA in gastric cancer tissues in comparison to normal controls (P<0.001)." (PMID 38149985, 2023). "In summary, upregulated expression of LACTB has been shown to prompt gastric cancer cells to adopt the EMT phenotype by impeding autophagy levels." (PMID 38149985, 2023). "UALCAN analysis indicated a marked increase in LACTB expression levels within gastric cancer tissues compared to normal controls." (PMID 38149985, 2023). "Interestingly, in OXA-resistant gastric cancer cells, LACTB overexpression, despite suppressing autophagy, effectively induces apoptosis." (PMID 39941048, 2025). "The impact of LACTB on the EMT of gastric cancer cells was assessed using Western blot analysis." (PMID 38149985, 2023). "LACTB was recently shown to play an important role in gastric cancer where it was described to induce apoptosis through the regulation of the autophagy-mediated mitochondrial pathway in oxaliplatin-resistant gastric cancer cells." (PMID 36282364, 2023). "Furthermore, we performed an ROC curve analysis of LACTB transcript 1 and found that the AUC was 0.6221 (95% CI: 0.5383-0.7059), indicating that LACTB transcript 1 can potentially serve as a biomarker for gastric cancer diagnosis." (PMID 38149985, 2023). "The findings demonstrated that gastric cancer cells with upregulated LACTB exhibited a significant increase in the number of cells migrating through the bottom and basement membranes of the Transwell chamber compared to the control group (P<0.001) for both HGC-27 and AGS cell lines." (PMID 38149985, 2023). "Experimental data indicated that a decreased level of LACTB could impede the migration and invasion of gastric cancer cells." (PMID 38149985, 2023).
gastric cancer (continued). "Taken together, these findings suggest that LACTB may play a role in the pathogenesis and progression of gastric cancer, potentially serving as an adverse prognostic factor for this disease." (PMID 38149985, 2023). "The findings from this investigation reveal that LACTB is upregulated in gastric cancer and may serve as a molecular marker for disease diagnosis." (PMID 38149985, 2023). "Indeed, attenuation of LACTB expression levels could impede the proliferation, migration, and invasion of gastric cancer cells." (PMID 38149985, 2023). "A similar phenomenon is observed in OXA-resistant gastric cancer cells (MGC-803/OXA), where LACTB overexpression inhibits autophagy." (PMID 39941048, 2025). "Conversely, low levels of LACTB have been observed to increase autophagy levels, which indirectly hinders EMT of gastric cancer cells and subsequently diminishes their migratory and invasive potential." (PMID 38149985, 2023). "Inhibition of LACTB expression in AGS cells resulted in a reduction in the invasive and migratory capacities of gastric cancer cells." (PMID 38149985, 2023). "Results demonstrated that upregulation of LACTB in AGS and HGC-27 gastric cancer cells promoted the migratory and invasive behavior of gastric cancer cells." (PMID 38149985, 2023). "The present study aimed to investigate the impact of LACTB expression modulation on the migration and invasion potential of AGS and HGC-27 gastric cancer cells." (PMID 38149985, 2023). "LACTB is downregulated in the oxaliplatin-resistant MGC-803 cells;Overexpressing LACTB reduces the resistance of gastric cancer cells to oxaliplatin." (PMID 36078157, 2022). "In summary, LACTB could potentially impact the EMT of tumor cells by modulating autophagy, subsequently affecting the migratory and invasive potential of gastric cancer cells." (PMID 38149985, 2023). "Subsequent research findings suggested that LACTB may attenuate EMT progression via modulation of autophagy levels, leading to inhibition of gastric cancer cell migration and invasion." (PMID 38149985, 2023). "Consequently, the present study sought to investigate the impact of LACTB on the expression levels of autophagy and EMT key proteins in gastric cancer cells by generating a gastric cancer cell model with LACTB overexpression or knockdown." (PMID 38149985, 2023). "Additionally, studies showed that in oxaliplatin (OXA)-resistant gastric cancer patients and those receiving neoadjuvant chemotherapy (NACT) with OXA plus S-1, LACTB expression is markedly downregulated, which is strongly correlated with poor treatment outcomes." (PMID 39941048, 2025).
glioblastoma (4 papers, 2023 to 2025). The most malignant astrocytic tumor (WHO grade IV). "Further investigations demonstrated that this decreased expression of LACTB in glioblastoma is strongly correlated with poor clinical outcomes." (PMID 39941048, 2025). "Beyond directly modulating epithelial and mesenchymal marker expression, elevated LACTB expression in glioblastoma was shown to reduce Rho-related GTP-binding protein RhoC (RHOC) protein levels, suppressing the RHOC/Cofilin signaling pathway." (PMID 39941048, 2025). "However, in glioblastoma, LACTB overexpression inhibits cancer cell proliferation." (PMID 37937197, 2023).
melanoma (4 papers, 2022 to 2025). A malignant, usually aggressive tumor composed of atypical, neoplastic melanocytes. "In melanoma cells, LACTB loss allows the catalytic subunit alpha of protein phosphatase-1 (PP1A) to effectively dephosphorylate YAP, leading to activation of the Hippo pathway and promoting tumorigenesis." (PMID 39941048, 2025). "Notably, in melanoma, a cancer type where LACTB is significantly downregulated and associated with poorer patient outcomes, restoring LACTB expression has emerged as a promising therapeutic approach due to its role in inducing apoptosis and modulating tumor growth." (PMID 39941048, 2025). "Research has demonstrated that the overexpression of LACTB effectively suppresses melanoma cell proliferation, migration, and invasion, while promoting apoptosis and inducing G2/M phase cell cycle arrest." (PMID 39941048, 2025). "The iDPP/LACTB nanocomplex has been specifically employed for the delivery of LACTB gene therapy into melanoma cells." (PMID 39941048, 2025). "It has been evidenced that SOX10 negatively regulates LACTB’s transcription in melanoma cells by binding to its promoter." (PMID 36078157, 2022). "In melanoma, delivery of LACTB via gene therapy showed promising results in both in vitro and in vivo models, where LACTB successfully inhibited cell cycle progression, induced G2/M cell cycle arrest, and enhanced apoptosis, further establishing its role in cell cycle regulation." (PMID 39941048, 2025). "In melanoma tissues, LACTB expression is markedly downregulated compared to normal skin cells." (PMID 39941048, 2025). "LACTB could suppress melanoma progression by attenuating PP1A and YAP interaction." (PMID 36531021, 2022).